NAGPA (N-acetylglucosamine-1-phosphodiester alpha-N-acetylglucosaminidase)
Description:
Catalyzes the second step in the formation of the mannose 6-phosphate targeting signal on lysosomal enzyme oligosaccharides by removing GlcNAc residues from GlcNAc-alpha-P-mannose moieties, which are formed in the first step. Also hydrolyzes UDP-GlcNAc, a sugar donor for Golgi N-acetylglucosaminyltransferases.
Synonyms: APAA; UCE
Tractability: Antibody: UniProt predicts a signal peptide or a membrane-spanning region. PROTAC: ubiquitination databases record sites on it; its protein half-life has been measured.
Target class: Enzyme; Phosphodiesterase
Gene: Protein-coding gene on chromosome 16 (5,024,756 to 5,034,141, reverse strand). Ensembl gene ENSG00000103174.
Subcellular location: Golgi apparatus, Golgi stack membrane; Golgi apparatus, trans-Golgi network
Gene Ontology:
Molecular function: protein binding; N-acetylglucosamine-1-phosphodiester alpha-N-acetylglucosaminidase activity
Biological process: carbohydrate metabolic process; lysosome organization; protein modification process; protein targeting to lysosome; secretion of lysosomal enzymes
Cellular component: membrane; Golgi apparatus; Golgi cisterna membrane
Genetic constraint (gnomAD): Loss-of-function variants: 59 observed, 49.04 expected, observed/expected ratio (o/e) 1.2, 90% interval 0.98 to 1.49. The synonymous counts are far from expectation, so gnomAD's model fits this gene poorly and the ratio says little. Missense variants: 888 observed, 705.89 expected, observed/expected ratio (o/e) 1.26, 90% interval 1.19 to 1.33. Synonymous variants: 399 observed, 297.8 expected, observed/expected ratio (o/e) 1.34, 90% interval 1.23 to 1.46.
Homologues: Orthologues: chimpanzee NAGPA (99% identical), macaque NAGPA (96% identical), dog NAGPA (86% identical), guinea pig NAGPA (84% identical), pig NAGPA (84% identical), rat Nagpa (81% identical), mouse Nagpa (81% identical), rabbit NAGPA (73% identical), tropical clawed frog nagpa (54% identical), zebrafish nagpa (50% identical), Drosophila melanogaster Ten-a (20% identical), Drosophila melanogaster Ten-m (20% identical), and 2 more. Paralogues in human: TENM3 (27% identical), TENM2 (27% identical), TENM4 (25% identical), TENM1 (23% identical).
Diseases named in the same sentence as NAGPA in open-access papers:
NAGPA is named in the same sentence as 14 diseases in open-access papers, as found by Europe PMC text mining. Sharing a sentence is not in itself a finding about the gene and the disease. The quoted sentences say what the papers report.
adolescent idiopathic scoliosis (1 paper, 2021). A scoliosis with no known cause arising in adolescent. "Moreover, the two genes FAM50B and NAGPA are associated with adolescent idiopathic scoliosis (GeneCards®), which is a common feature in MFS patients." (PMID 34895303, 2021).
dyslexia (1 paper, 2015). A learning disorder characterized by an impairment in processing written words. "As previous study reported association of GNPTAB, GNPTG and NAGPA with stuttering, we investigated these genes with dyslexia through association analysis." (PMID 25643770, 2015).
fronto-temporal dementia (1 paper, 2020). "In other neurodegenerative diseases, there is the strong association of heterozygous variants of PGN, the progranulin gene with fronto-temporal dementia and variants of GNPTAB, GNPTG, and the functionally related NAGPA gene with non-syndromic stuttering." (PMID 33005626, 2020).
language disorder (1 paper, 2015). A category of disorders characterized by an impairment in the development of an individual's language capabilities, which is in contrast to his/her non-verbal intellect. "Therefore, the three genes (GNPTAB, GNPTG and NAGPA) that may predispose people to stuttering are potential candidate risk genes for other speech and language disorders." (PMID 25643770, 2015).
liver cancer (1 paper, 2025). An epithelial or non-epithelial malignant neoplasm that arises from the liver. "NAGPA was found upregulated in liver cancer patients and was associated with poor prognosis." (PMID 38990489, 2025).
mucolipidosis (1 paper, 2017). A group of inherited lysosomal storage diseases characterized by accumulation of lipids and carbohydrates in the tissues, resulting in mental disabilities and skeletal malformations. "Interestingly, mutations in NAGPA have not been found in mucolipidosis or any other human disorder other than stuttering." (PMID 28361094, 2017).
speech disorder (1 paper, 2025). A term referring to disorders characterized by the disruption of normal speech. "Mutations in NAGPA, GNPTG, and GNPTAB have been associated with the speech disorder in Pakistani family members." (PMID 39857822, 2025).
stuttering disorder (1 paper, 2023). "It has been reported that point mutations in highly conserved locations in GNPTAB, GNPTG, and NAGPA genes were linked to stuttering disorders." (PMID 38020803, 2023). "It has been shown that specific point mutations in four genes that are involved in the lysosomal enzyme-targeting pathway (i.e., GNPTAB, GNPTG, NAGPA, and AP4E1) are linked to stuttering disorder, in which they may contribute to up to 20% of the cases (Frigerio;Domingues and Drayna, 2017)." (PMID 38020803, 2023).
tumor (2 papers, 2022 to 2025). "Of note, among the 6 proteins downregulated by NR-S:M in HepG2 cells, 5 of them (MRLP17, MDIG, GIPC1, NAGPA, FAM127A) were statistically and oppositely upregulated in LIHC vs. non-tumoral adjacent tumor (NTAT)." (PMID 38990489, 2025).
NAGPA also shares sentences with these, for which no sentence is quoted: neurodegenerative disease (2 papers); cancer (1); focal epilepsy (1); hepatocellular carcinoma (1); Sanfilippo B (1).